CCN2 (cellular communication network factor 2)
Diseases named in the same sentence as CCN2 in open-access papers (continued):
Sharing a sentence is not in itself a finding about the gene and the disease.
rheumatoid arthritis (12 papers, 2009 to 2023). A chronic, systemic autoimmune disorder characterized by inflammation in the synovial membranes and articular surfaces. "Nevertheless, the role of at least CCN1 and CCN2 in rheumatoid arthritis underscores their association with the regulation of proinflammatory cytokines in the microenvironment." (PMID 34228239, 2021). "Lessons learned from the proinflammatory role of CCN1 and CCN2 in rheumatoid arthritis should prompt studies on the ability of CCN family members to affect the tumour microenvironment and immune evasion." (PMID 34228239, 2021).
type 1 diabetes (12 papers, 2011 to 2025). "The expression of CCN family member 2 (CCN2) was dramatically increased in type 1 diabetes, which was accompanied by increased TGFβ, which was dependent on the protein kinase Cβ." (PMID 40458788, 2025). "For example, CCN1/CYR61 and CCN2/CTGF are basally increased in a mouse model for type-I diabetes, which presents myofiber atrophy and reduced capillary number to fiber ratio, evidencing decreased blood supply to the skeletal muscle." (PMID 34063397, 2021). "CCN2 was found to be negative by PCR in mononuclear cells from 120 children (age 1.8–15.8 years) with insulin-dependent diabetes mellitus (IDDM) and CD34+ cells from 100 cord blood samples." (PMID 27485291, 2016).
Cirrhosis (11 papers, 2007 to 2024). A chronic disorder of the liver in which liver tissue becomes scarred and is partially replaced by regenerative nodules and fibrotic tissue resulting in loss of liver function. "Taken together, these results indicated cross-species upregulation of Ccn2/Ctgf gene during hepatocyte damage, liver fibrosis, cirrhosis, and HCC development." (PMID 36469291, 2023). "In comparison of tumor fibrous stroma of HCC and benign fibrous stroma of the liver, the expressions of CCN2, EMA, and FAP were investigated in specimens of chronic hepatitis/cirrhosis (n = 36)." (PMID 25126747, 2014). "CCN2 expression was significantly related to background cirrhosis (P = 0.035), absence of tumor capsule (P = 0.049), and presence of tumor fibrous stroma in HCC (P = 0.028)." (PMID 25126747, 2014). "In this study, CCN2, epithelial membrane antigen (EMA), fibroblast activation protein (FAP), and keratin 19 (K19) expression was studied in 314 HCCs (cohort 1), 42 scirrhous HCCs (cohort 2), and 36 chronic hepatitis/cirrhosis specimens by immunohistochemistry." (PMID 25126747, 2014). "Subsequent multivariable analysis indicated background cirrhosis (HR = 1.815, P = 0.004) and vascular invasion (HR = 1.764, P = 0.015) as independent prognostic factors for DFS after surgery; CCN2 expression was not significant in multivariate analysis (HR = 1.561, P = 0.056)." (PMID 25126747, 2014).
proliferative diabetic retinopathy (11 papers, 2008 to 2026). Advanced retinopathy due to diabetes mellitus characterized by the formation of new vessels in the retina. "In patients with proliferative diabetic retinopathy (PDR), CCN2 correlated positively, and VEGF negatively, with the degree of fibrosis." (PMID 38886213, 2024).
diabetic cardiomyopathy (10 papers, 2017 to 2025). Diabetic cardiomyopathy is a disorder of the heart muscle in people with diabetes. "A previous study found that rats with STZ-induced diabetic cardiomyopathy overexpressed CCN2, which could be alleviated by N-acetylcysteine." (PMID 36465455, 2022). "In conclusion, increased CCN2 and fibronectin expression levels in parallel with STAT3 activation are identified in diabetic cardiomyopathy." (PMID 28672855, 2017).
disc degeneration (9 papers, 2017 to 2024). "CCN2 has also been ascribed a central role in intervertebral disc disease (IVD) which is the main cause of low back pain in adults: CCN2 downregulation associated with aging and CCN2 notochord-specific knockout leads to precocious and more pronounced degeneration." (PMID 34228239, 2021). "Similarly, levels of many matrix and matrix-related molecules e.g. Col2, Col9, HAS2, ccn2 are dysregulated during disc degeneration and genetic animal models have helped establish causative link between their expression and disc health." (PMID 33543030, 2020). "Interestingly, some researchers have reported finding that during degenerative disc disease, TGF-β suppresses CCN3 activity and upregulates CCN2 expression, a phenomenon that may be associated with a reparative response." (PMID 33919365, 2021). "Intermittent injection of PTH (iPTH) effectively attenuates disc degeneration of aged mice by direct signaling through NP cells, specifically improving intervertebral disc height and volume by increasing levels of TGF-β activity, CCN2, and aggrecan." (PMID 30038820, 2018). "The trend towards increased TGF-β expression during disc degeneration and reduction in CCN3 expression, accompanied by a simultaneous increase in CCN2 expression, may reflect a reparative response that enhances matrix synthesis and promotes changes in cell numbers." (PMID 33919365, 2021).
thyroid cancer (9 papers, 2014 to 2024). "In another study using thyroid carcinoma spheroids, the expression of CCN2 was downregulated, similar to that in our study." (PMID 34075058, 2021). "In thyroid cancer and rhabdomyosarcoma, CCN2 accelerates tumor growth and inhibits cell apoptosis." (PMID 29029514, 2017).
triple-negative breast carcinoma (9 papers, 2015 to 2024). An invasive breast carcinoma which is negative for expression of estrogen receptor (ER), progesterone receptor (PR), and human epidermal growth factor receptor 2 (HER2). "MMP3 overexpression enhanced CCN2/CTGF promoter activity in the human chondrosarcoma-derived chondrocytic cell line HCS-2/8 and non-basal type, triple-negative breast cancer cell line MDA-MB-231." (PMID 32260433, 2020).
acute lymphoblastic leukemia (8 papers, 2000 to 2022). Leukemia with an acute onset, characterized by the presence of lymphoblasts in the bone marrow and the peripheral blood. "Lymphoblast from both pediatric and adult B-acute lymphoblastic leukemias (B-ALL) show moderate to highly increased CCN2 mRNA expression compared with control cells (often CD34 positive cells, CD19+igM− cells or mononuclear cells) in the majority (60–80%) of cases." (PMID 33428075, 2021). "A human monoclonal antibody to CCN2, FG-3019, was initially used in treating a variety of tumors experimentally and showed antitumor activities in pancreas cancer, metastatic melanoma, and B-acute lymphoblastic leukemia (ALL)." (PMID 26421309, 2015).
cardiomyopathy (8 papers, 2012 to 2023). A disease of the heart muscle or myocardium proper. "Interestingly, despite the fact that cardiomyocyte is the major source of CTGF in the heart, the deletion of Ccn2 (the gene encoding CTGF) in cardiomyocytes failed to protect the heart from pressure overload-induced cardiomyopathy." (PMID 32435205, 2020).
gingival overgrowth (8 papers, 2011 to 2024). Excessive growth of the gingiva either by an increase in the size of the constituent cells (gingival hypertrophy) or by an increase in their number (gingival hyperplasia). "Phenytoin-induced gingival overgrowth is the most fibrotic form of gingival overgrowth and is associated with increased expression of CCN2, but a reduced presence of inflammatory cells." (PMID 32252793, 2020).
oral squamous cell carcinoma (8 papers, 2014 to 2022). "However, a contrary effect of CCN2 on ROS generation has also been described in Oral Squamous Cell Carcinoma cells, where CCN2 overexpression impaired mitochondrial oxidative phosphorylation." (PMID 34943123, 2021). "CCN2 also has a negative effect on cell growth in oral squamous cell carcinoma." (PMID 29029514, 2017).
amyotrophic lateral sclerosis (7 papers, 2014 to 2023). Amyotrophic lateral sclerosis (ALS) is a neurodegenerative disease characterized by progressive muscular paralysis reflecting degeneration of motor neurons in the primary motor cortex, corticospinal tracts, brainstem and spinal cord. "Improved neural functioning was also observed in the murine model of amyotrophic lateral sclerosis after CCN2 treatment, as evidenced by enhanced neuromuscular junction cell–cell communication." (PMID 37762168, 2023). "Inhibition of CCN2 gene expression reduced fibrosis and improved muscle and locomotor performance in a rodent model of amyotrophic lateral sclerosis." (PMID 34440643, 2021).
aneurysm (7 papers, 2015 to 2025). Bulging or ballooning in an area of an artery secondary to arterial wall weakening. "Considering the important role of SMC apoptosis in aneurysm pathology, we also studied the effects of CCN2 deficiency on apoptosis in cultured human primary aortic SMCs (HASMCs)." (PMID 36625347, 2023). "The proaneurysmal phenotype of CCN2SMCΔ mice is corroborated by a recent study using whole-body CCN2-deficient mice (inducible) in which augmented aneurysm development in both thoracic and abdominal aorta with Ang II infusion was observed." (PMID 36625347, 2023). "Firstly, we had described that CCN2 deletion led to aortic homeostasis disruption predisposed to aneurysm development." (PMID 36499730, 2022). "Contradictory to its profibrotic role in fibroblasts, CCN2 deficiency in SMC results in reduced elastin mRNA but increased breakage in aneurysm tissue that could compromise the overall strength of the vascular wall." (PMID 36625347, 2023). "Therefore, it is tempting to speculate that augmented aneurysm development in SMC-specific TGF-βR2 deficient mice might partially attribute to the disruption of signaling normally mediated by SMC-derived CCN2." (PMID 36625347, 2023). "Interestingly, we have recently demonstrated that the deletion of Ccn2 in adult mice alters vascular integrity and functions predisposed to aneurysm formation, which suggests a potential protective role of CCN2 in maintaining the aortic wall homeostasis under pathological conditions." (PMID 36499730, 2022). "In summary, our findings demonstrate that deficiency of SMC-specific CCN2 alters SMC phenotype and function to result in compromised vascular integrity and aneurysm development." (PMID 36625347, 2023). "Studies performed to date are inconclusive, as the levels of CCN2 expression reported in human aneurysms varies and is, at times, contradictory." (PMID 36625347, 2023). "CCN2 protein was expressed minimally in normal aortas yet was remarkably induced in aortas with aneurysms." (PMID 36625347, 2023). "Our data suggest that CCN2 is critical in maintaining an SMC contractile phenotype both in vivo and in vitro, and they show that deficiency of CCN2 leads to the loss of contractile markers in SMC and predisposes those mice to aneurysm development following vascular injury." (PMID 36625347, 2023). "It is unclear, however, whether a boost in CCN2 levels in the vasculature is a reparative mechanism to combat aneurysm progression, an agitator, or simply a consequence with little relevance of disease pathology." (PMID 36625347, 2023). "The results of this study are the first to our knowledge to demonstrate that the loss of SMC-specific CCN2 exacerbates aneurysm development in mice, both in the presence and absence of hypercholesterolemia." (PMID 36625347, 2023). "In the CCN2fl/fl group, 46% of the mice developed aneurysms in the suprarenal region of the abdominal aortas, while 91% of the SMC-specific CCN2-KO mice, henceforth CCN2SMCΔ mice, developed aneurysms exclusively in the infrarenal segments, the identical anatomic location where human AAA occurs." (PMID 36625347, 2023). "Notably, in CCN2SMCΔ mice, diminished expression of SMC markers was also evident in regions of the aorta with no aneurysm or dilations, suggesting intrinsic molecular changes associated with SMC CCN2 deficiency prior to the development of aneurysm." (PMID 36625347, 2023). "In the chronic Ang II setting, signals of SMMHC and αSMA are significantly diminished in the media layer of aortas at the aneurysm site in CCN2SMCΔ mice compared with those in both the aneurysm and nonaneurysm sites in CCN2-floxed control mice, henceforth CCN2fl/fl mice." (PMID 36625347, 2023).
bladder cancer (7 papers, 2017 to 2025). "CCN2 is mainly distributed in the extracellular matrix, as well as in cytoplasm of bladder cancer cells." (PMID 29029514, 2017).
liver disease (7 papers, 2010 to 2024). "We then analyzed the expression of ccn2, a matricellular protein that is upregulated in fibrotic hepatic disorders and sox9/krt19 expression, markers associated with chronic liver damage." (PMID 34413847, 2021). "The most intensively studied member of this family in experimental and human liver disease is CCN2/CTGF." (PMID 26779021, 2015). "In agreement with our findings, a recent study evaluating the role of CCN2 as a marker of fibrogenesis in liver disease also demonstrated extreme outliers in the control group." (PMID 20053285, 2010). "Increased platelet activation in advanced liver disease might also contribute to elevated CCN-2, since platelets contain large amounts of full length CCN-2 that is released upon activation." (PMID 27644406, 2016). "Hence reduced elimination might also contribute to accumulation of full length CCN-2 in advanced liver disease." (PMID 27644406, 2016).
lung disease (7 papers, 2009 to 2023). "•Fibroblast-specific deletion of CCN2 attenuates interstitial fibrosis and pulmonary vascular remodelling in models of lung diseases." (PMID 33662577, 2021). "In vivo studies were performed in mice using a conditional gene deletion strategy targeting CCN2 in a fibroblast-specific and time-dependent manner in two models of lung disease." (PMID 33662577, 2021). "Therefore, therapeutics aimed at blocking CCN2 function are likely to benefit several forms of severe lung disease." (PMID 33662577, 2021). "Together these data confirm that CCN2 plays a key role in promoting fibrosis and suggests that targeting CCN2 may be a viable option, at least for the treatment of human lung disease." (PMID 33662577, 2021).
Stroke (7 papers, 2012 to 2024). Sudden impairment of blood flow to a part of the brain due to occlusion or rupture of an artery to the brain. "Furthermore, an upregulation of CCN2/CTGF was found to be associated with reactive gliosis in stab-wounded rat brains or in the brain of stroke patients." (PMID 35493079, 2022).
aortic aneurysm (6 papers, 2021 to 2025). A ruptured aneurysm located in the wall of the proximal portion of the descending aorta proceeding from the arch of the aorta. "For instance, CCN2 deficiency predisposed to the formation of aortic aneurysms, whereas cardiac-specific overexpression of CCN2 and postischemic administration of recombinant CCN2 protected from acute myocardial IRI." (PMID 40362638, 2025). "While CCN2 deficiency is associated with increased risk of aortic aneurysm, its exact role in cardiac disease remains debated." (PMID 39273564, 2024). "In this sense, acquired CCN2 deletion in adult mice predispose to rapid aortic aneurysms development and rupture after Ang II administration." (PMID 35008801, 2021). "Although further research into the precise mechanisms regulating CCN2 expression by rs12526196C allele and its role in aortic aneurysm development and progression is needed, these results strength the main role of CCN2 as an essential factor in the aortic wall." (PMID 36499730, 2022). "In vascular pathologies, increase of CCN2 has been reported in atherosclerosis, aortic aneurysms, aorta dissection, and restenosis." (PMID 36625347, 2023). "Focusing on blood vessels, our group has recently demonstrated that CCN2 plays an essential role as a protective factor in the angiotensin-induced aortic aneurysm model." (PMID 36499730, 2022). "This study extrapolates to humans the relevance of CCN2 in aortic aneurysm observed in mice and postulates, for the first time, a potential protective role to CCN2 in aortic aneurysm pathology." (PMID 36499730, 2022). "In this sense, mutations in genes related to the TGF-β pathway activation, one of the main sources of CCN2 expression, are related to pathologies coursing with aortic aneurysm formation such as Marfan, Loeys–Dietz and Ehlers–Danlos syndromes." (PMID 36499730, 2022). "However, in part due to the lack of critical genetic evidence derived from transgenic animals, the precise physiological role of CCN2 from different cellular origins in vivo remains largely undefined for vascular diseases including aortic aneurysm." (PMID 36625347, 2023). "However, recent evidence from our group demonstrated the direct role of CCN2 in maintaining aortic wall homeostasis and acute and lethal aortic aneurysm development induced by angiotensin II in the absence of CCN2 in mice." (PMID 36499730, 2022).
ischemia (6 papers, 2009 to 2023). A hypoperfusion of the BLOOD through an organ or tissue caused by a PATHOLOGIC CONSTRICTION or obstruction of its BLOOD VESSELS, or an absence of BLOOD CIRCULATION. "In this context, this study deals with the acute or short term-effect of CCN2 in salvage of myocardial tissue during reperfusion following ischemia." (PMID 26872261, 2016). "Next, we evaluated the influence of hypoxia on the effects of CCN2 in our model of ischemia." (PMID 37973852, 2023). "Although we cannot rule out a direct effect of CCN2 on the HR, we have previously shown that administration of rhCCN2 to ex vivo perfused hearts immediately before onset of ischemia does not affect the HR after functional recovery has come to an end." (PMID 26872261, 2016).
leiomyoma (6 papers, 2007 to 2024). A well-circumscribed benign smooth muscle neoplasm characterized by the presence of spindle cells with cigar-shaped nuclei, interlacing fascicles, and a whorled pattern. "However, it does not support that connective tissue growth factor 2 (CCN2/CTGF) is a major mediator of TGFβ action in leiomyoma tissues." (PMID 25478164, 2014).
myopia (6 papers, 2013 to 2021). "In conclusion, our findings found that CCN2 signaling pathway plays an important role in the red flashing light-induced myopia in vivo." (PMID 23936844, 2013). "However, to what extent CCN2 gene of small effect and gene-environment interactions contribute to the development of myopia remains to be elucidated." (PMID 23936844, 2013). "The exact role of CCN2 in the progression of experimental myopia has yet to be determined." (PMID 23936844, 2013). "However, whether CCN2 signaling was involved in the red flashing light-induced myopia still remains unknown." (PMID 23936844, 2013). "We also investigated the expression of CCN2 and TGF in sclera tissues of the red flashing light-induced myopia model to explore their role in the pathogenesis of experimental myopia." (PMID 23936844, 2013). "From the CCN2 and TGF-β expression data and the change of refraction and axial length, the red flashing light could clearly promote ocular growth and induce myopia." (PMID 23936844, 2013). "However, it is still unknown whether CCN2 and TGF-β are also involved in the red flashing light-induced vision change and myopia." (PMID 23936844, 2013).
proliferative vitreoretinopathy (6 papers, 2008 to 2022). Vitreoretinal membrane shrinkage or contraction secondary to the proliferation of primarily retinal pigment epithelial cells and glial cells, particularly fibrous astrocytes, followed by membrane formation. "The accumulation of CCN2/CTGF is also found in the contractile membranes of proliferative vitreoretinopathy (PVR) patients and in subretinal fluid during retinal detachment." (PMID 36276919, 2022).